HLA-G (major histocompatibility complex, class I, G)
Diseases named in the same sentence as HLA-G in open-access papers (continued):
Sharing a sentence is not in itself a finding about the gene and the disease.
tumor (continued). "None of the HLA-G 3’UTR haplotypes were associated with high/low tumor burden or other clinical disease status pre-NACT." (PMID 35095919, 2021). "In the present work, we described (a) the structure and three main forms of HLA-G, (b) summarized the mechanism of HLA-G in the immune escape of tumor cells, (c) discussed the potential role of HLA-G as a tumor marker, and reviewed (d) the methods for detecting and quantifying HLA-G." (PMID 34868081, 2021). "However, inter-patient, inter-tumor, and intra-tumor heterogeneity of the HLA-G expression in each histopathological type of malignancies is also evident." (PMID 34276691, 2021). "It is therefore important to limit the development of post-transplant cancer, as HLA-G and PD-L1 may favor the immune escape of tumor cells." (PMID 34938293, 2021). "Thus, HLA-G molecule exhibits highly variable expression among tumor types, with marked intertumoral heterogeneity." (PMID 34276642, 2021). "Consequently, HLA-G has been proposed as a candidate target for immune checkpoint inhibitor (ICI) tumour therapy by various studies." (PMID 34361031, 2021). "Comparable to HLA-G, HLA-E can be expressed on tumor cells, stroma cells or both." (PMID 34201079, 2021). "Here, we used CRISPR/Cas9 gene editing to disrupt HLA-G gene expression in tumor cell lines." (PMID 34773056, 2021). "Additionally, promising results have been shown in halting the progression and eradication of HLA-G1-expressing tumour cells using CAR-T cells directed specifically against HLA-G in an in vivo mouse model." (PMID 34361031, 2021). "This competitive ability may be due to the affinity of anti-HLA-G CAR scFv for HLA-G protein on tumor cells, which is higher than that of HLA-G for inhibitory receptors on NK cells." (PMID 34663641, 2021). "Such conflicting survival results indicate that HLA-G may have different biological roles in different tumor types." (PMID 34276642, 2021). "HLA-G expression by tumour cells may also play such a role, resulting in tumour immune evasion, making HLA-G a potential target for immunotherapies." (PMID 34361031, 2021). "The status of HLA-G in tumor tissues is usually detected by IHC." (PMID 34868081, 2021). "Interestingly, also a positive correlation between tumour samples that stained strongly for HLA-G and HLA-class I expression was observed." (PMID 34361031, 2021). "However, by combining tumour HLA-G expression with other factors such as classical HLA-class I tumour status, significantly poor clinical patient outcome was demonstrated." (PMID 34361031, 2021). "In previous preclinical investigations, blocking tumour cell-expressed HLA-G or immune cell surface ILT2/4 with specific antibodies could restore the functions of NK cells or T cells against target cells." (PMID 34938296, 2021). "Additionally, future research should focus on the role of HLA-G in tumour-immune interactions, as this is a multifactorial and complex process." (PMID 34361031, 2021). "However, no discrimination can currently be made between the different HLA-G isoforms in the tumour lesions when 4H84 (or any mAb that recognises all HLA-G isoforms for that matter) is used as HLA-G-detecting mAb." (PMID 34361031, 2021). "In addition, HLA-G is secreted in a variety of body fluids, as either free soluble HLA-G (sHLA-G) or part of extracellular vesicles (EVs), and it has been extensively studied as tumor markers." (PMID 34868081, 2021). "Thus, we investigated the expression level of HLA-G in tumor and normal tissues by immunohistochemistry (IHC) staining and quantified the H score." (PMID 34663641, 2021). "Statistically significant, as well as nonsignificant associations between tumour HLA-G expression and clinical outcome of patients were observed." (PMID 34361031, 2021). "Wide discordances concerning the association between tumour HLA-G expression and clinical patient outcome were also reported independent of the percentage of HLA-G-positive tumour samples and used methods." (PMID 34361031, 2021).
tumor (continued). "Increased expression of HLA-G correlated with tumor node metastasis staging." (PMID 34276691, 2021). "Similarly, human activated NK cells capture HLA-G from tumor cells, and NK cells that acquire HLA-G cease proliferation and reduce their cytotoxic capacity." (PMID 34069602, 2021). "In addition, analysis from the CCLE database was consistent with these results, confirming that HLA-G is ectopic expressed in most human tumor cells." (PMID 34276642, 2021). "Interestingly, in studies where similar HLA-G quantification methods were used, considerable differences in the percentage of HLA-G-positive tumour samples and clinical patient outcome were observed." (PMID 34361031, 2021). "This may indicate a potential functional role for HLA-G in modulating tumour-immune responses, potentially culminating in disease progression of patients with GC." (PMID 34361031, 2021). "No other apparent links could be distinguished between the percentage of HLA-G-positive tumour samples and clinical outcome of patients." (PMID 34361031, 2021). "Therefore, studying the presentation of peptides by HLA-G can give more insights in the biological function of HLA-G and the interaction with its receptors, both in healthy and tumor tissue." (PMID 33213057, 2020). "As HLA-G is known to be present in the tumor microenvironment, it could inhibit iNKT cell reactivity to αGC and impair the effectiveness of the iNKT cell-based immune therapy." (PMID 33505397, 2020). "Also, it was demonstrated that the tumor cells were able to modify their HLA-G isoform expression profile in order to modify their susceptibility against NK cells." (PMID 32922387, 2020). "Furthermore, HLA-G expression tends to disappear after surgical excision of tumor lesion requiring to develop new culture approaches to maintain HLA-G expression ex vivo." (PMID 32922387, 2020). "Indeed, HLA-G plays the role of an immune escape mechanism through inhibition of anti-tumor effectors, alteration of cytokine expression patterns, and generation of regulatory cells." (PMID 33505397, 2020). "Since HLA-G is abnormally and specifically expressed in tumor tissues, it may represent a checkpoint in tumor immunology." (PMID 33193435, 2020). "As a result, the receptors will only be blocked when HLA-G is expressed by the tumor." (PMID 33213057, 2020). "This expression was associated with an immune evasive phenotype, increased cell motility and invasion, suggesting that HLA-G could be involved in tumor escape." (PMID 32922387, 2020). "Surface expression of HLA-G may represent an additional mechanism through which tumor cells escape the immune response, although its relevance in CLL is still controversial." (PMID 32155826, 2020). "Thus, even if HLA-G expression is weak or diffuse within the tumor, the administration of anti-HLA-G blocking antibodies should dampen the immune-protective effects of HLA-G." (PMID 32922387, 2020). "Moreover, HLA-G expression in samples from different zones of a same tumor also varied significantly when detected with a distinct anti-HLA-G antibody." (PMID 33329527, 2020). "Therefore, HLA-G not only exerts immunosuppressive effects on macrophages and NK cells but also drives reprogramming into tumor-promoting cells." (PMID 33425752, 2020). "HLA-G is a molecule involved in fetal-maternal tolerance and in tumor immune escape." (PMID 33505397, 2020). "One can hypothesize that a switch between HLA-G isoforms expressed occurred following the development of the tumor." (PMID 32922387, 2020). "Therefore, tumor microenvironmental factors, such as hypoxia, stress, hormones, and inflammation, have been proposed to activate HLA-G expression in tumor cells." (PMID 33425752, 2020). "Aberrant HLA-G expression in cervical lesions could generate inhibitory signals in the cancer microenvironment, which would ultimately help tumor cells escape from immunosurveillance and reshape tumor progression and metastasis." (PMID 32670296, 2020).
tumor (continued). "HLA-G has a broader inhibitory effect than any other checkpoint since it can block all steps of anti-tumor responses by acting on natural killer (NK) cells, B lymphocytes, T lymphocytes and antigen-presenting cells (APC) through direct interaction with its receptors." (PMID 32620162, 2020). "Current data suggested that HLA-G gene polymorphisms (mainly located in the coding region or 3′UTR region) appear to be independent risk factors for HPV infection and cervical carcinogenesis, which supports the biological role of HLA-G molecules in shaping the tumor microenvironment." (PMID 32670296, 2020). "Indeed, in the context of cancer, HLA-G can be expressed by the tumor cells and/or by the infiltrating APCs (monocytes/macrophages/DC)." (PMID 33505397, 2020). "The role of HLA-G as a checkpoint allowing tumor escape has been demonstrated in murine models." (PMID 32620162, 2020). "Interestingly, HLA-G− tumor cell lines were efficiently lysed by activated NK cells in vitro and perhaps became resistant to NK cell-mediated lysis when transduced with HLA-G1." (PMID 32707982, 2020). "There are several cis-regulatory elements present in the promoter region of HLA-G gene which may respond to specific signals from the tumor microenvironment." (PMID 33425752, 2020). "HLA-G expression has also been correlated with IL-17 expression that could, on one hand, inhibit tumor progression by increasing the immune response, and on the other hand increase angiogenesis." (PMID 32922387, 2020). "Moreover, percentage of HLA-G expression probed with different anti-HLA-G antibodies also varies dramatically within a tumor." (PMID 33329527, 2020). "HLA-G is considered an important immune checkpoint in cancer due to its strong immune-inhibiting functions, and thereby, it is able to facilitate immune escape and tumor growth." (PMID 33213057, 2020). "As we do not observe an effect of IFN-γ on the expression of HLA-G it is unlikely that IFN-γ could be an independent inducer of HLA-G in the tumor microenvironment at lower concentrations." (PMID 32560316, 2020). "Therefore, to evaluate the clinical significance of HLA-G expression in cancers, important issues including location of the tumor tissues isolated, HLA-G isoforms and specificity of the anti-HLA-G antibodies should be concerned." (PMID 33329527, 2020). "Therefore, immunotherapy targeting HLA-G can have two potential effects as it can restore both anti-tumor functions of immune cells and inhibit tumor growth." (PMID 33213057, 2020). "While immune cells are inhibited when HLA-G binds to its receptors, tumor cells might profit from the expression of both HLA-G and its receptors." (PMID 33213057, 2020). "It has been observed that HLA-G expression is gradually downregulated or even lost during long-term culture of primary tumor cells, which provides direct evidence for this hypothesis." (PMID 33425752, 2020). "HLA-G expression in tumor cells and cells chronically infected with virus may enable them to escape from host immune surveillance." (PMID 32670296, 2020). "Findings also revealed that HLA-G expression in ovarian cancer cells could enhance the tumor cell migration and metastasis in tumor-bearing immunodeficient nude mice through induction of matrix metalloproteinase-15 (MMP-15) expression." (PMID 33329527, 2020). "Our work demonstrates that HLA-G and myeloid regulatory cells such as HLA-G-expressing DC-10 cells prevent proper activation of iNKT cells by αGC, a mechanism that may very well occur in iNKT cell-based anti-tumor therapy trials and reduce therapy efficiency." (PMID 33505397, 2020). "Furthermore, for T cells, HLA-G protein expression was directly correlated with the tumor grade and stage." (PMID 32922387, 2020). "Fortunately, HLA-G expression can be downregulated through RNA interference or antibody blockade, which can allow recovery of the functions of immune effectors and prevent tumor reoccurrence." (PMID 32670296, 2020).
tumor (continued). "HLA-G turns to be a major advantage for tumor cell survival and development." (PMID 32922387, 2020). "HLA-G expression positively correlated with the presence of tumor-infiltrating Tregs." (PMID 33425752, 2020). "However, their results on the HLA-G expression levels were different in the tumor microenvironment (TME)." (PMID 32922387, 2020). "In addition, cancer cells can induce HLA-G-expressing immune cells (e.g., transferring HLA-G to T cells through trogocytosis) within the tumor microenvironment." (PMID 32983083, 2020). "In addition, co-expression of HLA-G and its receptors has been observed in different cancer types, leading to proliferation, migration and invasion of tumor cells upon interaction." (PMID 33213057, 2020). "The different isoforms might constitute different functional forms of HLA-G, also emphasized by a marked heterogeneity in isoform expression observed within the same tumor for some cancers." (PMID 32560316, 2020). "HLA-G expression was more frequently observed in advanced disease stage and tumor grade." (PMID 33425752, 2020). "HLA-G expression was sharply differed either between samples or inside a tumor tissue." (PMID 33329527, 2020). "Moreover, human leukocyte antigen G (HLA-G)+ T cells with an inhibitory activity comparable to natural Treg can be generated in BM of MM patients after tumor plasma cell–T cell interaction by trogocytosis of immunosuppressive molecules such as HLA-G." (PMID 33194767, 2020). "HLA-G presents peptide fragments on the surface of tumor cells, binds to several different proteins expressed by both lymphocytes and innate immune cells, and has well-documented associations with immune suppression and poor prognosis in a variety of tumor types." (PMID 33348579, 2020). "Therefore, the role and functions of HLA-G in tumor immune escape and tumor development is beyond a hypothetical mechanism, its involvement and relevance has been widely documented." (PMID 32922387, 2020). "Analysis of the immune responses following the tumor progression released that HLA-G promoted accumulation and suppressive activity of MDSCs in HLA-G+ tumor-bearing mice through engagement of the paired immunoglobulin like receptor-B (PIR-B), the homolog of human ILTs." (PMID 33425752, 2020). "Indeed, the estimation of HLA-G's actual expression in tumor tissue is limited, particularly concerning the presence and percentage of the new non-canonical isoforms, for which detection antibodies are scarce or inexistent." (PMID 32922387, 2020). "First, through intercellular transfer, HLA‐G− tumor cells can uptake HLA‐G molecules from adjacent HLA‐G+ tumor cells in a cell‐to‐cell contact‐dependent manner by trogocytosis, and TnTs transfer or can uptake the HLA‐G antigen derived from distant HLA‐G+ tumor cells carried by exosomes." (PMID 31489189, 2019). "Moreover, intercellular transfer of tumor cell‐derived HLA‐G among immune cells can also extensively amplify its immune suppression effects, leading to a broader tumor cell population resistance to antitumoral immunity." (PMID 31489189, 2019). "IL-10 can also be synthesized by tumor cells and, in turn, upregulates the expression of HLA-G." (PMID 31013867, 2019). "HLA-G-expressing T cells are also observed in the tumor microenvironment promoting a tolerogenic immune milieu, but as with other immunological mechanisms having the same effect during pregnancy and cancer development, a favorable effect is actually opposite in the two settings." (PMID 31134056, 2019). "Interestingly, in EWS, the MHC class I molecule HLA-G expressed locally on tumor cells and tumor-infiltrating lymphocytes (TILs) has been studied as an immune regulator." (PMID 31311607, 2019). "In addition, blocking of HLA-G on tumor cells in patients with chronic lymphocytic leukemia (CLL) increased their susceptibility to NK cell-mediated cytotoxicity." (PMID 31847387, 2019).
tumor (continued). "HLA-G is an important complex molecule that plays an important role in facilitating tumour escape from immune surveillance by its immunosuppressive function on T and NK cells, and the aberrant expression of HLA-G has been reported to be related to a variety of tumours." (PMID 30962267, 2019). "Indeed, patients with high levels of HLA-GEV had a reduced PFS, pointing to the notion that HLA-G-bearing EV facilitate or support tumor escape from the immune system." (PMID 31382533, 2019). "It seems that the high HLA-G expression induces tumor cells toward progressive stages." (PMID 31286981, 2019). "Therefore, in a model of metastatic ovarian cancer, HLA-G has been reported to support tumor progression by reducing NK cell cytotoxicity." (PMID 30939820, 2019). "As a consequence, the HLA‐G− tumor cells turn into HLA‐Gacq+ tumor cells." (PMID 31489189, 2019). "Improved understanding of HLA-G regulation will contribute to the development of strategies modulating its expression and to optimizing the design of (immune-) therapeutic strategies for the treatment of tumor patients." (PMID 30932005, 2019). "Based on these reports, the unidirectional and bidirectional intercellular transfer of HLA‐G can occur from tumor cells to tumor cells, from tumor cells to immune effectors and from immune cells to immune cells, which can play critical roles in tumor advancement." (PMID 31489189, 2019). "HLA-G has immunosuppressive functions during the tumor progression." (PMID 31286981, 2019). "This may be due to the immune-suppressive property of HLA-G to inhibit proliferation and cytotoxic activity of tumor infiltrated T- and NK cells." (PMID 31013867, 2019). "As certain HLA-G 3′UTR SNPs are associated with a worse clinical outcome, here, HLA-G 3′UTR typing or HLA-G expression in tumor lesions may improve the prediction of clinical outcome and thus, the disease management." (PMID 30932005, 2019). "In summary, increasing evidence has revealed that, in addition to HLA‐G expressed on tumor cells, intercellular transfer of HLA‐G among different types of tumor cells and immune cells plays important roles in the regulation of immune responses and in enriching cancer cell immune evasion strategies." (PMID 31489189, 2019). "Different cohort sizes and clinicopathological parameters such as treatment history, tumor subhistological type and tumor immune microenvironment could all affect the evaluation of the status of HLA-G expression among cancer patients." (PMID 30319626, 2018). "This study was implemented to determine if iron and HLA-G, as neglected molecules enhance tumor immunosuppression, and could be cancer immunotherapy targets." (PMID 30400822, 2018). "A potential explanation for the limited detection of HLA-G in only a proportion of EwS is that HLA-G expression in tumor tissues may be a dynamic event and may vary between different areas in individual tumors." (PMID 29464090, 2018). "Interestingly, the surrounding lymphocytes and histiocytes were HLA-G positive and correlation with disease progression suggests an association of these immunoreactive patterns of HRS cells and the tumor microenvironment on disease outcome." (PMID 29602958, 2018). "Even though the primary source of HLA-G was unclear, it was postulated that the presence of HLA-G-expressing DC-10 is involved in sustaining the expression of HLA-G on blasts contributing to inhibition of the immune system promoting tumor immune-escape." (PMID 29686676, 2018). "HLA-G expression on tumor cells was determined by immunohistochemistry upon autopsy." (PMID 29464090, 2018). "Strategies that modulate HLA-G expression in the tumor microenvironment may enhance the efficacy of cellular immunotherapeutics in this cancer." (PMID 29464090, 2018). "However, in the tumor microenvironment, the increased amount of soluble HLA-G has an immunosuppressive effect." (PMID 29467963, 2018).